CCL20 (C-C motif chemokine ligand 20)
Diseases named in the same sentence as CCL20 in open-access papers (continued):
Sharing a sentence is not in itself a finding about the gene and the disease.
tumor (continued). "Employing an anti‐CCL20 neutralizing antibody and Foxp3DTR mice, it is demonstrated that CCR6+Foxp3+ regulatory T cells (Tregs) recruited by Gal1‐induced TAMs contributed to reduced infiltration and dysfunctional state of CD8+ T cells, subsequently facilitating tumor progression." (PMID 39853961, 2025). "Interestingly, knockdown of Cxcl3, but not of Ccl20, notably increased the frequency and activity of tumor-infiltrating granzyme B+ (GzmB+) CD8+ T cells." (PMID 40179015, 2025). "Notably, CCL20 and its receptor CCR6 are important in tumor microenvironment interactions." (PMID 39985603, 2025). "Additionally, the characteristic expression profile of this cell subgroup included multiple myeloid cell activation markers, such as IL1RN, CXCL8, CCL20, and the chemokines CCL3 and SPP1, indicating the activated state of myeloid cells in the tumour microenvironment." (PMID 40539065, 2025). "Additionally, CCL20 and CXCL8 secreted by tumor cells into the tumor microenvironment (TME) were found to promote the recruitment of Treg cells and reduce CD8+ T cell infiltration, thereby facilitating tumor immune evasion." (PMID 40463392, 2025). "The expression levels of ccl-2 (MCP-1), ccl-20 (MIP-3), ccl-7 (MCP-3), CXCL-4 (PF-4), CXCL 1 (Gro -), and CXCL-12 (SDF-1) are also significantly increased in replicative senescent cells, allowing the disruption of the blood-tumor barrier integrity and greater spread of tumor cells." (PMID 37450933, 2024). "Notably, in tumor models, Th9 cells aid in promoting cytotoxic CD8+ T cells expansion and activation, through CCL20/CCR6-dependent recruitment of type 1 dendritic cells (DC1), specialized for the cross-presentation of antigen by MHC class I molecules to CD8+T cells." (PMID 39104410, 2024). "Moreover, the macrophage-derived proinflammatory chemokines, namely CC-chemokine ligand 20 (CCL20) and macrophage inflammatory protein-3α (MIP3α), all bind CC-chemokine receptor 6 (CCR6) on PDAC cells, leading to upregulated MMP-9 expression and tumor invasion." (PMID 37444617, 2023). "Then, tumor volume was monitored for one month, The results of in vivo LDA demonstrated that the frequency of tumor-initiating cells was increased approximately six-fold in the group of 4T1 cells co-cultured with CCL20-modulated PMN-MDSCs in comparison to the pSIN group." (PMID 36859354, 2023). "However, abundant CCL20 is not found on the surface of tumor tissues of all NSCLC patients, although it has been confirmed that it is highly expressed in adenocarcinoma tissues." (PMID 36982500, 2023). "Furthermore, CCL20 and/or CCR6 proteins were found to be highly expressed in lung, cervical, gastric, ovarian cancer tissues, and renal cell carcinoma, facilitating tumor proliferation and directional migration through autocrine or paracrine modes." (PMID 35702353, 2022). "Similarly, the INHBA+ macrophage subset co-expressed pro-tumorigenic molecules such as IL6, TGFβ, TIMP1, CCL20, CXCL1, and IL10, highlighting the highly plastic and complex nature of tumor-infiltrating myeloid cells in vivo, consistent with recent similar studies in other solid tumors." (PMID 36439171, 2022). "Ddx5 was increased in the whole skin lesions of MC903- or IMQ-treated Cd93–/– mice compared with their wild-type counterparts, along with fewer plaques on the ears or dorsal skin and reduced expression of Il4, Il13, Ccl11, Ccl17 and Ccl22 or Cxcl1, Cxcl2, Ccl20, Il23, Il17a and Il36γ." (PMID 36271146, 2022). "Moreover, CCL20 and CCR6 comprise a chemokine regulatory axis to regulate the behavior of cancer cells and immune cells concurrently, thereby shaping tumor immune microenvironment (TIME) states and influencing the combat between the immune system and the tumor." (PMID 35864953, 2022).
tumor (continued). "Consistently, LLC and MC38 tumor-infiltrating CD11c+ MHCII+ CD11b+ Ly6c+ CXCL10+ DCs were significantly increased in CD45+ cells in the RORγt agonist-treated group compared with the vehicle group, and CCL20 levels were higher in RORγt agonist-treated tumor tissue compared to vehicle treated tumors." (PMID 35459193, 2022). "Furthermore, silencing either CCL20 or HuR in triple-negative breast cell lines significantly abrogated the tumor-promoting effect." (PMID 34569432, 2021). "Thus, the CCL20/CCR6 axis is involved in the development of inflammatory diseases and tumor angiogenesis, but its role remains unknown in vascular disorders, including SSc vasculopathy." (PMID 34774095, 2021). "The chemokine MIP‐3a (CCL20) may mediate recruitment of macrophages and thus affect tumour growth." (PMID 32910558, 2020). "Thus, we have previously considered an in vivo strategy by which endogenous DCs are attracted to the tumor sites using a live tumor cell to express a DC chemokine, the macrophage inflammatory protein-3α (MIP-3α or CCL20), which proved to be effective in several murine tumor models." (PMID 32759233, 2020). "High CCL20 expression and increased FOXP3+ TILs infiltrates were both associated with high histological grade, axillary lymph node metastases, positive HER2, and high Ki67 index but not correlated with age, tumor size, ER status." (PMID 31852159, 2019). "The transcription of Tnfα, Cxcl1, Ccl2, and Ccl20 was upregulated in Spont-PyMT tumors, like in Trans-PyMT ones, even though the fold increases were not always similar in the two tumor types." (PMID 31511510, 2019). "However, Treg cell-mediated tumor growth was blocked by anti-CCL20 antibody, which itself had no influence on tumor growth and 5-FU-mediated effects." (PMID 31395078, 2019). "Through analysis of paired tumor and non-tumor liver samples from HCC patients, an immunosuppressive gradient has been described with increased expression of chemokine networks such as CXCR3/CXCL10 and CCR6/CCL20 which enhances macrophage and Treg recruitment to the liver." (PMID 31627733, 2019). "One chemokine that can drive immune cells towards the tumor is the Macrophage Inflammatory Protein-3 alpha (MIP3α; CCL20) which attracts cells expressing CCR6/CD196 such as (memory) T cells, natural killer cells and immature dendritic cells (DCs), all of which can mediate tumor regressions 16-19." (PMID 31588231, 2019). "They found that CCL20 secreted by tumor cells strongly influences the frequencies of immune-suppressive regulatory Treg cells and TH17 populations, thereby supporting the fact that inhibition of the CCR6/CCL20 duo presents a novel therapeutic strategy in cancer treatment." (PMID 30453514, 2018). "Moreover, Ccl20 and Ccr6 increased in obese control tumours and were downregulated in non-tumour tissue and tumours of obese IL-6Rα-deficient mice." (PMID 29695802, 2018). "Our data verified that suppression of the functions of CCL20 molecules derived from cancer cells and surrounding non-cancer cells inhibited tumor growth in bone marrow, as well as severe osteolysis, in mice inoculated with MDA-MB-231 cells through the left cardiac ventricles." (PMID 28851919, 2017). "Other immune cells in tumor microenvironment may also promote DC recruitment, such as Th9 cells, which increase DC infiltration of the tumor mediated by CCR6/CCL20 interaction that generates CD8(+) cytotoxic T lymphocyte (CTLs) responses and inhibit tumor growth." (PMID 25110692, 2014). "In addition, CCR6/CCL20 interaction in endometrial adenocarcinoma, CXCR1/2/CXCL7 interaction in clear cell renal cell carcinoma, CXCR2/CXCL8 interaction in nasopharyngeal carcinoma, and CXCR6/CXCR16 interaction in HCC are reported to promote tumor cell growth." (PMID 25110692, 2014).
tumor (continued). "Thus, we propose that once tumor cells express CCR6, their migration and metastasis behavior could be greatly enhanced by stimulating with CCL20 produced by macrophages or other immune cells in the tumor microenvironment." (PMID 24979261, 2014). "We have previously identified IL-1α to be the main tool used by the tumor cells to activate CAFs to produce several inflammatory factors (e.g., IL-6, CCL20, CXCL8, COX-2, and VEGF-A), and this could be one mechanism the tumor cells use to escape elimination by the immune system." (PMID 22190968, 2011). "Tumor tissue stained positive for CCL20 while tumor adjacent lung tissue was negative." (PMID 21949768, 2011). "However, at the protein level, there was up-regulation of CXCL5/ENA78, CCL20/MIP3-α, IGFBP3, OPN and TIMP1 in tumours and their PN, indicating that these could be early events in the gastric tumorigenesis." (PMID 21092330, 2010). "However, it was also revealed that CCL20 may play a protective role and inhibit NSCLC tumor growth." (PMID 37316552, 2023). "Therefore, RORγt agonists may accelerate CCL20 production through signaling to Type 17 T cells to attract DC cells, resulting in an elevation of CXCL10 levels and immune CD8+ T cell infiltration in the tumor." (PMID 35459193, 2022). "Notably, tumor cells expressed relatively high levels of chemokines (e.g., CCL20, CCL19, and CXCL10), while the corresponding receptors were widely expressed in immune cells, suggesting that these chemokines play significant roles in enhancing immune cell infiltration into NPC tumor tissue." (PMID 32686767, 2020). "In the current study, we used anti-CCL20 antibody to investigate tumor growth in vivo and found that blockade of CCL20 suppressed tumor progression and restored 5-FU sensitivity in CRC, suggesting that the FOXO1/CEBPB/NF-κB/CCL20 axis may be a potential therapeutic target for CRC." (PMID 31395078, 2019). "Although the tumor microenvironment (TME) is critical in cancer biology, this study did not extensively explore the impact of the CCL20/CCR6 axis on the immune TME." (PMID 40444282, 2025). "After removing the individual samples from the database, we obtained 20 pairs of paired samples and then compared the expression levels of CCL20, SCG5, SPP1, FOLR3, and KRT75 genes in tumor tissues vs. normal tissues." (PMID 36684241, 2022). "In a large CRC cohort, tumor-infiltrating IL17-producing cells have not worsened clinical outcome and recruit highly cytotoxic CCR5+CCR6+CD8+ T cells via the release of CCL5 and CCL20." (PMID 32707869, 2020). "On the contrary, we did not found increased expression of CCL17 and CCL20, the two specific ligands of CCR4, in tumor tissue." (PMID 25768730, 2015). "When compared to exosomes from tumor cells without heat stress (TEX), heat-stressed tumor cell-derived exosomes (HS-TEX) had more chemokines (CCL2, CCL3, CCL4, CCL5, and CCL20), HSPs (HSP60, HSC70, HSP70, and HSP90), and adhesion molecules (e.g., CD54 and CD86)." (PMID 35158999, 2022). "For CCL20, we observed elevated expression in HCC cell lines upon treatment with DAC, but not in non-tumor cell lines, suggesting that CCL20 methylation status may be specifically associated with HCC prognosis." (PMID 26300991, 2015). "Therefore, one could speculate that both markers, CCL20 and CXCL8, discriminate advanced tumor stages rather than detecting early HCC and predict poor prognosis." (PMID 36982370, 2023). "Unexpected results enhancing mRNA levels of CCL20 rather than CXCL1/2 in CXCR2-driven ovarian progression indicate the diversity and complex of chemokine network between cell culture system with homogenous interaction and tumor progression via heterogeneous interaction with other cell types." (PMID 27723802, 2016). "In addition, HERC5 and CCL20 mRNAs were significantly negatively correlated (p = 0.0003) in the PTs of HCC patients who experienced tumor recurrence and not in the PTs of HCC patients who did not experience tumor recurrence (p = 0.49)." (PMID 26653219, 2015).
cancer (269 papers, 2005 to 2026). A tumor composed of atypical neoplastic, often pleomorphic cells that invade other tissues. "The chemokine CCL20 is implicated in inflammation and cancer but has proven challenging to target therapeutically." (PMID 42039489, 2026). "Similar to this study, Smad4 silencing in epithelial cells promoted the expression of CCL20, thereby enabling susceptibility to colitis-associated cancer." (PMID 39346534, 2024). "It is known to migrate into esophageal tissues, inducing inflammation and the release of chemokines, such as CCL20, and has been associated with the development and prognosis of cancer recurrence." (PMID 38280026, 2024). "A total of 73 genes with pearson correlation coefficient (PCC) ≥ 0.30 were found, in which cancer-associated chemokines CCL20, CXCL8 and CXCL3 were extremely associated with CXCL1 expression." (PMID 35764974, 2022). "The intratumoral infiltration of C-C motif chemokine receptor 6 (CCR6)+ cells was associated with favorable prognosis in some human CCL20-producing cancers." (PMID 36726985, 2022). "This revealed that expression of several cancer-associated proteins, including GM-CSF, CCL20 and VCAM1, was strongly dependent on MALT1 catalytic activity in PC3 cells." (PMID 36009554, 2022). "Recent studies have shown that high levels of CCL20 are associated with malignancies of various cancers." (PMID 36147484, 2022). "Macrophages and cancer cells acquire close interaction in association with the progression of oral carcinogenesis, and CCL20 secretion is induced in OSCC cells." (PMID 34178651, 2021). "Increased CCL15 and CCL20 expression has been reported in a number of cancers and is associated with a poor prognosis." (PMID 32560387, 2020). "Univariable Cox regression analysis showed that inguinal nodal status (P<0.001), pelvic LNM (P<0.001), T stage (P=0.021), and higher preoperative serum CCL20 level (P<0.001) were associated with shorter cancer specific survival in our PC cohort." (PMID 33123272, 2020). "The pathogenic role of CCL20-induced CCR6 signaling is particularly well established in cancer." (PMID 38472446, 2024). "Thus, cancer cells can stimulate their own proliferation and migration in an autocrine manner, as well as cause angiogenesis via the binding of CCL20 to CCR6." (PMID 34659370, 2021). "In breast carcinoma, CCL20 has also been associated with the epithelial-to-mesenchymal transition that may participate in cancer cell invasiveness/metastasis." (PMID 33924428, 2021). "In conclusion, serum CCL20 level might serve as a potential diagnostic and prognostic cancer biomarker for PC." (PMID 33123272, 2020). "These types of cancers, which are known to mainly involve the mucosal tissue and shown CCL20 expression, were designated as mucosal-associated cancers (MACs) in the present study, while the other cancers, such as thyroid, breast, and liver cancer, were designated as non-MACs." (PMID 27517754, 2016). "Moreover, CCL20 is associated with a poor prognosis and resistance to chemotherapy and has recently been reported as enhancing the self-renewal and stemness of cancer stem cells." (PMID 33924428, 2021). "IL-8 enhances angiogenesis and neutrophil infiltration, while CCL20 and its related signaling networks support cancer stemness and metastatic dissemination." (PMID 42245673, 2026). "Increasing evidence has shown that chemokines including CCL20 are important orchestrators of fibroblast-mediated cancer progression." (PMID 39985603, 2025). "Cancer cells expressed multiple SASP-associated CC (e.g., CCL20) and CXC (e.g., CXCL1, CXCL8, CXCL16) chemokines, which have been shown to be induced by radiotherapy in preclinical models." (PMID 40811032, 2025). "In contrast, CCL20 overexpression in cancer cells resulted in an increase in Cox2 and Arg1 expression." (PMID 38297161, 2024). "We observed decreased CCL20 expression in Cat D KO cancer cells, which increased following TGFBI blockade." (PMID 38297161, 2024).
cancer (continued). "CCL20 expression was rescued by Cat D addition and increased in a dose-dependent manner in response to iTGFBI treatment of Cat D KO cancer cells." (PMID 38297161, 2024). "Another chemokine involved in angiogenesis is C-C motif chemokine ligand 20 (CCL20), which was found to induce the proliferation, invasion, and in vitro tube formation of different cancer cells through the interaction with its receptor CCR6." (PMID 38927538, 2024). "The lack of an effect of TGFBI treatment on TAM polarization under culture conditions without CM further highlighted the biological necessity of TGFBI-mediated CCL20 in CM from Cat D KO cancer cells." (PMID 38297161, 2024). "We found that BaP was able to upregulate PD-L2, which bound RGMB to activate NFκB and induced secretion of chemokine CCL20, leading to recruitment of Tregs to promote cancer progression." (PMID 39042313, 2024). "Lower expression of Cox2 and Arg1 and reduced CD204+ polarization were observed in the THP-1 cells cultured with CM from the CCL20 siRNA-transfected cancer cells compared with those from the cells cultured with CM from the cont siRNA-transfected cancer cells." (PMID 38297161, 2024). "CM was collected from the cont siRNA- and CCL20 siRNA-transfected cancer cells and treated with M0 THP-1 cells." (PMID 38297161, 2024). "Our results provide a direct link between the LUBAC and LTβR-induced activation of canonical NF-κB signaling and secretion of IL-8 and CCL20 by cancer cells." (PMID 39215104, 2024). "Our RNA-sequencing results indicated that the cancer cell-secreted chemokine CCL20 is a major secretory chemokine for Cat D-TGFBI-mediated TAM polarization." (PMID 38297161, 2024). "Many studies have shown that highly expressed CCL20 participates in the progression and migration of numerous cancers, including HCC." (PMID 38493218, 2024). "At the mRNA and protein levels, the expression of CCL20 in cancer tissues was higher in CRC samples than in normal tissues using the TCGA, GEO and CPTAC databases." (PMID 38809918, 2024). "CCL20 expression is upregulated in many cancers, such as breast cancer, hepatocellular carcinoma and pancreatic cancer." (PMID 37092451, 2023). "Here, we observed that polymorphonuclear myeloid-derived suppressor cells (PMN-MDSCs) were remarkably enriched in TME of CCL20-overexpressing cancer cell orthotopic allograft tumors." (PMID 36859354, 2023). "CCL20 expression is also elevated in other cancers, such as pancreatic cancer, colorectal cancer, and ovarian cancer." (PMID 35408440, 2022). "M2-like TAMs secrete CCL20 to activate CCR6 in cancer cells to enhance metastasis of primary melanoma." (PMID 35672862, 2022). "CCL20 also contributes to the progression of many cancers by activating various signaling proteins, especially NF-κB." (PMID 36012347, 2022). "In cancer research, CCL20 plays a crucial role in neoplastic processes, and TAM is its major source." (PMID 36387204, 2022). "C-C motif chemokine 20 (CCL20) has been found to have a crucial role in cancer as a mediator by interacting with C-C motif chemokine receptor 6 (CCR6)." (PMID 36439472, 2022). "Mechanistically, CCL20 produced by cancer cells can render the cell itself to a more malignant phenotype." (PMID 35864953, 2022). "CCR6 has a unique ligand CCL20 (MIP-3α) which is expressed in many healthy tissues but also by cancer cells and M2 TAMs." (PMID 36429101, 2022). "Specifically, the CCL20 module displayed an AUC = 0.65 (P = 0.002) for discriminating normal from cancer in Cohort-1, and an AUC = 0.7 (P = 0.11) in Cohort-2, the non-significance in Cohort-2 attributable to the much smaller sample size of Cohort-2." (PMID 35164838, 2022). "Considering the combination of CCL20 and TGF-β is associated with patients' worse prognoses and TGF-β plays a driver role in the cancer EMT 17, we raise that EMT is the predominant mechanism by which CCL20 promotes LUAD." (PMID 35864953, 2022).